NLRP3 (NLR family pyrin domain containing 3)
Diseases named in the same sentence as NLRP3 in open-access papers (continued):
Sharing a sentence is not in itself a finding about the gene and the disease.
aneurysm (11 papers, 2018 to 2024). Bulging or ballooning in an area of an artery secondary to arterial wall weakening. "It remains possible, however, that the pharmacologic inhibition of NLRP3 with MCC950 causes decreased aneurysm rupture by acting on cell types other than monocyte/macrophages." (PMID 41541085, 2023). "We found that NLRP3+ cells are more abundant in murine aneurysm tissue than in the healthy cerebral vasculature, which supported the idea that NLRP3 was associated with aneurysm pathology." (PMID 41541085, 2023). "To determine if pyroptosis plays a role in human and mouse aneurysms, we evaluated markers of pyroptosis including NLRP3, CASP1, GSDMD and IL‐1β, and also analysed MMP2/9 in human aortic aneurysms and mouse AAA." (PMID 39601144, 2024). "CircHipk3 serves a dual role in augmenting macrophage pyroptosis by interaction with Stat3, increase the NLRP3 level, and by binding Snd1 to promote Ptbp1 mRNA degradation to inhibit autophagy, thereby inducing aneurysm formation and progression." (PMID 39601144, 2024). "In human aneurysm specimens, we also found that both pyroptosis markers (NLRP3, GSDMD and CASP1) and circHipk3 were mainly concentrated in the adventitia of aneurysm tissue, which was the main site of macrophage infiltration." (PMID 39601144, 2024). "Further, aneurysm tissue also demonstrated higher mRNA expression levels of the NLRP3 pathway components caspase-1, IL-1β, and GSDMD." (PMID 41541085, 2023). "To further study the relationship between NLRP3 and aneurysm rupture, we used our established murine model of cerebral aneurysm rupture." (PMID 41541085, 2023). "Our aim for this experiment was to confirm NLRP3 expression in murine aneurysm tissue, as it has previously only been documented in human aneurysm tissue." (PMID 41541085, 2023). "The NLRP3 inflammasome is one such target that we aimed to evaluate for its role in aneurysm rupture." (PMID 41541085, 2023). "The aneurysm tissue had 14.1 (95% CI: 7.6–25.4) NLRP3+ cells per high-powered field compared to just 0.5 (95% CI: −0.7–1.7) cells/HPF in the healthy cerebral vessel control tissue (p = 0.01, n = 3–4 each)." (PMID 41541085, 2023). "This study explored NLRP3 as a mediator of aneurysm pathology by testing the ability of the NLRP3 inhibitor MCC950 to prevent aneurysm rupture." (PMID 41541085, 2023). "First, we investigated the expression of the NLRP3 pathway in aneurysm tissue vs. healthy cerebral vessels." (PMID 41541085, 2023). "Our results indicate that the NLRP3 inflammasome contributes to aneurysm rupture and macrophage polarization within the vessel wall." (PMID 41541085, 2023). "Studies in NLRP3 knockout murine models have shown reduced aortic destruction and aneurysm formation, suggesting the NLRP3-caspase-1 inflammasome is contributory in aortic aneurysm formation." (PMID 38275364, 2023). "The NLRP3 inflammasomes have been shown to be expressed in human sIA walls, and even more so in ruptured aneurysms." (PMID 34534311, 2021). "Conceptually, our data indicates that the pathology of aneurysm progression is associated with NLRP3 pathway regulation; however, we did not directly measure the effect of MCC950 treatment on this pathway." (PMID 41541085, 2023). "Overall, these results support our hypothesis that NLRP3 inhibition prevents aneurysm rupture and suppresses pro-inflammatory macrophage phenotype polarization." (PMID 41541085, 2023). "We hypothesized that NLRP3 inhibition via MCC950 would protect against aneurysm rupture, decrease the M1/M2 macrophage ratio, and reduce the IL-1β expression in the vessel walls." (PMID 41541085, 2023). "We hypothesized that NLRP3 inhibition via MCC950 treatment would impede aneurysm progression and rupture." (PMID 41541085, 2023). "While these findings are only correlative, they suggest that the NLRP3 inflammasome could be a favorable target for aneurysm research for several reasons." (PMID 41541085, 2023).
aneurysm (continued). "Finally, NLRP3-NF-κB interactions are well documented, supporting the idea that NLRP3 inhibition could suppress the pro-inflammatory M1-type phenotype polarization of macrophages observed in aneurysms." (PMID 41541085, 2023). "The mRNA expression of the downstream NLRP3 pathway components caspase-1, IL-1β, and GSDMD is also increased in the aneurysm tissue compared to healthy vessels." (PMID 41541085, 2023). "In the setting of aneurysm rupture, erythrocyte lysis and the release of soluble factors into the bloodstream compounded with BBB disruption can promote NLR family pyrin domain-containing 3 (NLRP3) inflammasome activation." (PMID 39195261, 2024). "Further, since hemodynamics and systemic blood pressure are central to aneurysm progression, we wanted to rule out decreased systemic blood pressure as an indirect way that NLRP3 inhibition affects aneurysm rupture." (PMID 41541085, 2023). "Our finding that naringenin or TFEB inhibited NLRP3 inflammasome activation and reduced IL-1β secretion during AAA is consistent with previous reports that depletion of the NLRP3, caspase-1, and IL-1β inflammasomes protect against aneurysm formation in mice." (PMID 35228523, 2022). "Three hub genes, NLRP3, IL1B and IL18, were identified using Cytoscape software and the WGCNA correlation module, and external validation revealed statistically significant differences between the expression of these hub genes in the ruptured and unruptured aneurysm groups (p < 0.05)." (PMID 37752552, 2023). "Altogether, these findings suggest a general participation of canonical NLRP-3-dependent pyroptosis as well as non-canonical pyroptosis in multiple aneurysmal diseases, indicating great potential of pyroptosis as novel target for aneurysm prevention." (PMID 34895131, 2021).
autoimmune hepatitis (11 papers, 2018 to 2025). Hepatitis caused by autoantibodies. "Over-activation of the NLRP3 inflammasome has also been found in trichloroethene- and ConA-induced autoimmune hepatitis mice models, indicating that the inflammasome activation-dependent IL-1β and pyroptosis contributed to exacerbating the liver injury." (PMID 36160411, 2022). "Similarly, blocking NLRP3 and IL-1β is one of the therapeutic strategies for the treatment of autoimmune hepatitis." (PMID 40367564, 2025). "In a mouse model with autoimmune hepatitis (AIH) induced by hepatic injection of S100 protein, miR-223 in the exosomes derived from bone marrow mesenchymal stem cells (BMSCs) protected the liver from injury and inhibited NLRP3 activation that causes hepatic damage and liver dysfunction." (PMID 35884901, 2022). "In mice with autoimmune hepatitis (AIH), the inhibition of NLRP3 inflammasome-mediated pyroptosis-derived IL-1β led to a decreased accumulation of CD68-positive cells and CD11b-positive cells in liver tissue." (PMID 38380334, 2024). "Exosomes and exosomesmiR-223(+) significantly reversed autoimmune hepatitis by downregulating cytokines such as NLRP3 and caspase-1, while exosomesmiR-223(−) did not exert protective effects in the experimental model of autoimmune hepatitis." (PMID 32883343, 2020).
bacterial sepsis (11 papers, 2017 to 2025). "Reticulocalbin 3 (Rcn3) regulates the NF-κB/NLRP3/inflammasome axis, thereby protecting AECs and alleviating bacterial Sepsis-Associated ALI." (PMID 40842982, 2025). "In summary, in addition to regulating inflammatory responses, NLRP3 also plays a key role in apoptosis, pyroptosis, and other forms of programmed cell death in bacterial Sepsis-Associated AEC injury." (PMID 40842982, 2025). "The NLRP3 inflammasome is known to be activated by Staphylococcus aureus, one of the leading causes of bacteremia worldwide." (PMID 31403210, 2019). "However, the specific molecular mechanisms and how NLRP3 regulates these processes in bacterial Sepsis-Associated ALI still require further investigation." (PMID 40842982, 2025). "But it was unclear whether this agent has any potential effects on NLRP3 inflammasome activation, which has been implicated in many inflammatory conditions ranging from metabolic disorders to bacterial sepsis." (PMID 29375379, 2017). "These enzymes regulate the ubiquitination and deubiquitination of key proteins such as GPX4, NLRP3, and AUF1, with their modulation offering potential therapeutic benefits in mitigating AEC injury and bacterial Sepsis-Associated ALI progression." (PMID 40842982, 2025). "In bacterial sepsis, endotoxins activate the NLRP3 inflammasome in both macrophages and AECs, promoting AEC apoptosis, pyroptosis, and the release of inflammatory cytokines." (PMID 40842982, 2025). "As a major compound of SB, scutellarin has exhibited NLRP3 inflammasome suppression, thereby rescuing mice from bacterial sepsis." (PMID 34063247, 2021). "Scutellarin is a natural flavonoid; it has been reported to inhibit NLRP3 inflammasome activation in macrophages and protect mice against bacterial sepsis by augmenting protein kinase A signaling." (PMID 31595205, 2019). "Inhibiting NLRP3 inflammasome activation in macrophages helps to protect mice against bacterial sepsis." (PMID 31595205, 2019). "In line with the finding that baicalin inhibited NLRP3 inflammasome activation in vitro, baicalin administration in vivo significantly improved the survival of mice in bacterial sepsis." (PMID 29163487, 2017). "Those previous studies and our data indicated that baicalin robustly inhibited NLRP3 inflammasome activation to attenuate inflammatory responses during infections such as bacterial sepsis." (PMID 29163487, 2017). "In addition, the mRNA expression of NLRP3, CASP1, and IL1B was altered in patients with SAB compared with healthy controls, indicating a modified priming state of the NLRP3 inflammasome during bacteremia." (PMID 31403210, 2019). "We showed in this study that baicalin markedly inhibited NLRP3 inflammasome activation in murine macrophages upon ATP stimulation, suggesting that baicalin may attenuate the severity of bacterial sepsis." (PMID 29163487, 2017). "Furthermore, our data also suggest that scutellarin can be used to treat bacterial sepsis probably by blocking NLRP3 activation in the early stage of bacterial sepsis." (PMID 29375379, 2017). "Besides, oral administration of scutellarin significantly attenuated systemic inflammation and improved the survival of mice with bacterial sepsis, suggesting that it could inhibit NLRP3 activation in vivo." (PMID 29375379, 2017). "This study therefore aimed to investigate NLRP3 inflammasome activity in 20 patients with S. aureus bacteremia (SAB), by repeated measurement during the first week of bacteremia, compared with controls." (PMID 31403210, 2019). "In contrast to NLRP3 expression, the mRNA level of IL1B was higher in whole blood from patients with SAB compared with controls during the first days of bacteremia, with significant differences on days 1, 2, and 3 (p = .001, p = .004, and p = .021, respectively)." (PMID 31403210, 2019).
bacterial sepsis (continued). "In total, whether under basal conditions or after ex vivo stimulation, the NLRP3 inflammasome showed diminished activation and reactivation abilities in both monocytes and PMN of patients with viral and bacterial sepsis, which appeared to be more marked upon admission." (PMID 38140660, 2023). "As IL-1β secretion in vivo upon Gram-negative bacterial infection has been shown to be NLRP3 dependent, these results suggested that scutellarin protected mice against bacterial sepsis probably by suppressing NLRP3 inflammasome activation upon microbial infection." (PMID 29375379, 2017). "In total, whether under basal conditions or after ex vivo stimulation, the NLRP3 inflammasome diminished activation and reactivation abilities of both monocytes and PMN was more pronounced in non-survivors compared with survivor patients with viral and bacterial sepsis." (PMID 38140660, 2023).
brain edema (11 papers, 2015 to 2025). Increased intracellular or extracellular fluid in brain tissue. "This modulation significantly reduced NLRP3-driven inflammatory responses, attenuated cerebral edema, and improved neurological outcomes." (PMID 40083546, 2025). "ICH-induced NLRP3 inflammasome activation can promote neutrophil infiltration, trigger the inflammatory response, impair neurological functions and aggravate brain edema after ICH." (PMID 36558410, 2022). "ICH can induce gut microbiota dysbiosis, and inhibition of the NLRP3 inflammasome can relieve brain edema and attenuate corticospinal tract injury by changing the bacterial community structure in ICH patients." (PMID 36558410, 2022). "Nevertheless, ICH-induced NLRP3 inflammasome activation can promote neutrophil infiltration, trigger the inflammatory response, impair neurological functions and aggravate brain edema after ICH." (PMID 36558410, 2022). "We found that BBG treatment inhibited the inflammatory response via the P2X7R/NLRP3 axis following ICH, and this was associated with significantly improved neurological function and less brain edema." (PMID 26475134, 2015). "Accumulating evidence that NLRP3 inflammasome inhibition could relieve neuroinflammation, disrepute BBB intensity, and reduce cell death in early brain injury make the NLRP3 inflammasome-induced anti-inflammatory treatment be a potential strategy to reduce brain edema." (PMID 35620574, 2022). "Increased expression of the MST4 gene suppresses NLRP3 inflammasome activation following ICH, leading to a decrease in pro-inflammatory cytokine release, which in turn helps to reduce cerebral edema and improve neurological function." (PMID 40083546, 2025). "As a pivotal regulator of the innate immune system, NLRP3 is activated after ICH, which can boost the inflammatory response by the release of IL-1β and facilitate neutrophil infiltration, thus radically exacerbating brain edema." (PMID 34413820, 2021).
cerebrovascular diseases (11 papers, 2018 to 2025). "By inhibiting microtubule polymerization and suppressing the NLRP3 inflammasome, colchicine reduces the production of pro-inflammatory cytokines such as interleukin-1β and interleukin-6, both of which have been implicated in the pathogenesis of cerebrovascular disease." (PMID 41407975, 2025). "IFN-β acts as an anti-inflammatory agent in cerebrovascular disease by inhibiting NLRP3 inflammasome activity." (PMID 36676165, 2023). "This would expand our current knowledge of the NLRP3 inflammasome as well as potential therapeutic strategies for CSVD as arguably the most prevalent age-related cerebrovascular disease." (PMID 36676165, 2023). "The NLRP3 inflammasome has been shown to be a crucial component in neurological diseases including cerebrovascular diseases." (PMID 33923537, 2021). "In cerebrovascular diseases, several agents taking advantage of inhibiting the NLRP3 inflammasome have been presented in the alleviation of ischemic or hemorrhagic stroke." (PMID 30233319, 2018). "Taken together, although current studies have provided potentially effective agents for the treatment of cerebrovascular diseases targeting on the NLRP3 inflammasome, further studies are demanded for the exploration of their applications in clinic." (PMID 30233319, 2018). "The NLRP3 inflammasome has been reported to play a vital role in cerebrovascular diseases, and many signaling pathways mediated by the NLRP3 inflammasome are highly involved in the onset and progression of both ischemic and hemorrhagic stroke." (PMID 30233319, 2018). "NLRP3 has been a therapeutic target in the treatment of cerebrovascular diseases." (PMID 38216560, 2024). "Nrf2 alleviates cerebrovascular disease by inhibiting NLRP3 inflammasome activation." (PMID 36818726, 2022). "The NLRP3 inflammasome is the most characteristic in the NLR family and was found to participate in neurodegenerative diseases and cerebrovascular diseases." (PMID 35807002, 2022). "The NLRP3 inflammasome has evolved into one of the most important components of the cerebral immune system that offers plausible mechanistic roles in the natural history of CSVD heterogeneous manifestations specifically, and cerebrovascular disease in general." (PMID 36676165, 2023). "Several specific drugs or compounds may target specific NLRP3 inflammasome components and inhibit the activation and action of the NLRP3 inflammasome that could prove beneficial for neuroprotective strategies of CSVD and other cerebrovascular diseases." (PMID 36676165, 2023). "Evidence of NLRP3 implication in cerebrovascular diseases is not confined to preclinical data." (PMID 29654318, 2018).
chronic heart failure (11 papers, 2019 to 2025). "Pyroptotic signaling involving nuclear factor-kappa B (NF-κB) and NOD-like receptor family pyrin domain–containing 3 (NLRP3) has been implicated in chronic heart failure (CHF)." (PMID 41458951, 2025). "In summary, NLRP3 inflammasome activation is implicated in the generation and exacerbation of chronic heart failure (CHF)." (PMID 38650918, 2024). "According to a recent study, MLK3 can promote pyroptosis of cardiomyocytes primarily via NFκB/NLRP3 signaling pathway, aggravating myocardial fibrosis in the early stages of chronic heart failure (CHF)." (PMID 35990979, 2022). "Monocytes derived from chronic heart failure patients carrying DNMT3A mutations revealed a significantly increased expression of inflammasome genes, such as NLRP3 and IL-1β, compared with the monocytes isolated from chronic heart failure patients with no DNMT3A mutations." (PMID 34299198, 2021). "Moreover, non-NLRP3 inflammasomes, including NLRC4 and AIM2, contribute to the development of chronic heart failure." (PMID 37239853, 2023).